VCAM1 (vascular cell adhesion molecule 1)
Diseases named in the same sentence as VCAM1 in open-access papers (continued):
Sharing a sentence is not in itself a finding about the gene and the disease.
aneurysm (10 papers, 2013 to 2025). Bulging or ballooning in an area of an artery secondary to arterial wall weakening. "With our system, we have experimentally demonstrated how slight geometric alterations in and of themselves cause differential VCAM-1 expression, which correlates with aneurysm expansion." (PMID 26202603, 2015). "In addition, in vivo longitudinal molecular MRI studies revealed vascular inflammation strongly associated with the aneurysm area, i.e., high expression of VCAM-1 and P-selectin adhesion molecules, which precedes and predicts the bleeding extent in the case of IA rupture." (PMID 38500201, 2024). "Additionally, our in vivo longitudinal molecular MRI studies of VCAM-1 and P-selectin adhesion molecules revealed vascular inflammation in the IA area prior to aneurysm formation." (PMID 38500201, 2024). "In addition, recent preclinical work identified Tregs as promising immunotherapeutic targets: a 2025 study using CAR-Treg cells directed against VCAM-1 demonstrated attenuation of aneurysm progression, indicating that modulation of Treg number or function may help limit disease development." (PMID 41303525, 2025). "The increased EC expression of MCP-1 and vascular cell adhesion molecule 1 (Vcam-1) recruits macrophages into the aortic wall and leads to ECM degradation and, finally, aneurysm formation." (PMID 35207478, 2022). "In addition to ICAM-1, other cell adhesion molecules, such as vascular cell adhesion molecule-1 (VCAM-1) and E-selectin, have shown to be increased in the CSF of patients following aneurysm rupture." (PMID 24724095, 2014). "Significant increase of LDL, cholesterol, triglycerides and circulating inflammatory cells was observed in the Ang II-treated animals, and gene expression studies showed that ICAM-1, VCAM-1, MCP-1, M-CSF, MMP-2, MMP-9 and MMP-12 were upregulated in the aorta of aneurysm-induced mice." (PMID 23826202, 2013).
angina (10 papers, 2013 to 2025). "The findings indicated that elevated VCAM-1 levels were a strong predictor of major adverse cardiovascular events, including new coronary incidents, hospitalizations for angina, and cardiac death." (PMID 40599142, 2025). "There are limited studies on correlations of the peripheral and coronary blood levels of GDF-15 and VCAM-1, but a study of stable and unstable angina patients identified significant linear correlations between the serum levels of hsCRP in the left forearm vein and coronary sinus for both groups." (PMID 39830114, 2024). "Elevated plasma levels of ICAM-1 were associated with the risk of AMI, coronary death, and angina during follow-up, an outcome not observed when serum levels of VCAM-1 were assessed." (PMID 31778438, 2019). "Secondary outcome parameters: other circulating inflammatory markers (including IL-6, TNFα, VCAM-1, CD40, sCD40L, MCP-1, and MMP-9), improvement in symptoms of angina and blood stasis syndrome, and safety." (PMID 23983803, 2013). "Regarding ACS, a study that included 75 patients measured circulating levels of ICAM-1 and VCAM-1, VCAM-1 showed to be a powerful predictor of major events in this patient profile; however, a new coronary event, hospitalization for angina, or cardiac death were considered adverse outcomes." (PMID 31778438, 2019). "The involvement of hsCRP has been reported in patients with angina symptoms but without significant coronary obstruction (NOCAD), but little is known about the involvement of GDF- 15, and more information regarding VCAM-1 is also needed." (PMID 39830114, 2024).
cerebrovascular disease (10 papers, 2015 to 2024). "The association between hypomethylation and the expression of VCAM-1 may be a link for cardiovascular and cerebrovascular diseases." (PMID 35741740, 2022). "Vascular cell adhesion molecule 1 (VCAM1), an endothelial-specific marker, is related to inflammation in cerebrovascular disease." (PMID 34867389, 2021). "It has also been reported that in patients with acute cerebral ischemia, plasma levels of VCAM1 can remain elevated over a 3-month period, showing a protracted inflammation in patients who have experienced cerebrovascular disease." (PMID 33971895, 2021).
cognitive decline (10 papers, 2019 to 2026). "This indicates that VCAM-1 is a candidate biomarker for vascular inflammation associated with and potentially contributing to cognitive decline during AD." (PMID 31427644, 2019). "Likewise, CSF markers of endothelial injury, including ICAM‐1 and VCAM‐1, were elevated in preclinical AD in relation to CSF tau, cortical thinning, and cognitive decline." (PMID 41319164, 2025). "Our study's findings contribute to the existing literature by suggesting that inflammatory markers (TNF-α and IL-1ß) and endothelial cell markers (E-selectin, ICAM-1, and VCAM-1) have neither cross-sectional nor longitudinal associations with cognitive decline in AD patients." (PMID 39085534, 2025). "We investigated the relationship between baseline circulating levels of inflammatory (TNF-α, IL-1ß) and endothelial cell markers (VCAM-1, ICAM-1, E-selectin) and 18-month cognitive decline (ADAS-cog12) in 266 mild-to-moderate AD patients from the NILVAD study." (PMID 39085534, 2025). "Animal studies have suggested that interference with VCAM-1 expression intensity—and, therefore, improvement of BBB leakproofness and a reduction in neuroinflammation—could have neuroprotective and anti-aging properties, even with improvement of age-related cognitive decline." (PMID 41225971, 2025).
eosinophilia (10 papers, 2010 to 2025). "The CysLTs increase expression of adhesion molecules such as VCAM-1 associated with eosinophilia as a result of reducing eosinophil apoptosis." (PMID 30781605, 2019). "Complete abrogation of eosinophilia was observed in ICAM-1/VCAM-1 double KO mice after allergen challenge, demonstrating the direct regulation of endothelial-eosinophil interactions governing eosinophilia." (PMID 23378838, 2013). "For instance, eotaxin recruits eosinophils through VCAM-1, leading to tissue eosinophilia." (PMID 40943070, 2025). "One hypothesis suggests that dupilumab‐induced eosinophilia results from altered vascular cell adhesion molecule‐1 (VCAM‐1) expression, a key molecule mediating eosinophil adhesion to endothelial cells." (PMID 40492692, 2025). "The expression of vascular cell adhesion molecule-1, which is recognized by eosinophil ligands, has been shown to be inhibited by the use of PPIs, providing an explanation for the response of eosinophilia in an acid-independent manner." (PMID 36968499, 2023). "ICAM-1, VCAM-1) and tissue eosinophilia in both the upper and lower airway." (PMID 33376573, 2020). "Impaired tissue homing might be the cause for blood eosinophilia, as migration of eosinophils to tissues, but not their bone marrow egress or production, is dependent on IL-4/IL-13-induced eotaxins and vascular-cell adhesion molecule-1." (PMID 32344789, 2020). "In addition, GAL-3 has also been studied in eosinophilia, and the GAL-3 expression by eosinophil cells supports the cell adhesion to VCAM-1 and integrin and rolling to the site of inflammation." (PMID 20699002, 2010).
injury (10 papers, 2017 to 2025). Damage inflicted on the body as the direct or indirect result of an external force, with or without disruption of structural continuity. "Skin injury activates adhesion molecules VCAM-1 and ICAM-1 in endothelial cells, and triggers the subsequent release of chemokines and inflammatory cell infiltration." (PMID 35335455, 2022). "Endothelial damage identified by elevated plasma syndecan-1 and soluble vascular cell adhesion molecule-1 (sVCAM-1) was present in all trauma-induced shock groups." (PMID 33685634, 2021). "The expressions of ICAM-1 and VCAM-1 have been reported to be increased in toxic and BD-induced models of acute lung injury but remained unchanged in the present study as reported by other authors." (PMID 28753621, 2017). "After kidney injury, VCAM-1, GFP, SDF -1/CXCR4, and CD44 are upregulated in the injured tissue, which may play important roles in the migration of MSCs to the damaged area." (PMID 33424979, 2020).
type 1 diabetes (10 papers, 2011 to 2024). "This study aimed to evaluate the serum level of netrin and soluble vascular cell adhesion molecule 1 (VCAM-I) in patients with type IΙ diabetes mellitus (T2DM) and evaluate the association of their levels with the development of a diabetic complication." (PMID 34179515, 2021). "In vivo, type-1 diabetes modeled in rats caused increased TXNIP in peripheral blood along with decreased NO and VEGF, increased ROS, and increased inflammation-associated vascular cell adhesion molecule 1 (VCAM-1)." (PMID 33302545, 2020).
acute coronary syndrome (9 papers, 2013 to 2025). Signs and symptoms related to acute ischemia of the myocardium secondary to coronary artery disease. "Serum ICAM-1 levels are linked to macrovascular disease, and serum VCAM-1 concentrations have been correlated with the occurrence of acute coronary syndrome." (PMID 25955252, 2015). "In conclusion, circulating VCAM-1 might be associated with the extent of coronary lesions in patients with a risk of developing acute coronary syndrome." (PMID 29846413, 2018). "For example IL-4, a cytokine classically produced by Th2 cells, has been proposed as protective in ATH, but IL-4 also increases the expression of P-selectin, VCAM-1, and matrix metalloprotease 1 and 12, which are implicated in aortic aneurysm formation and in acute coronary syndrome." (PMID 23533763, 2013). "This study aimed to investigate the association between circulating VCAM-1 levels, LV volumes, and LV ejection fraction (LVEF), quantified using three-dimensional echocardiography (3-DE), in patients with acute coronary syndrome (ACS)." (PMID 40599142, 2025). "In a study involving 75 patients with acute coronary syndrome, researchers assessed circulating levels of VCAM-1." (PMID 40599142, 2025). "Results showed that serum EphA2, VCAM-1, and Hcy levels in acute coronary syndrome patients were significantly higher than those in chronic coronary syndrome patients (p = 0.000; p = 0.000; p = 0.033, respectively)." (PMID 33510642, 2020). "Soluble VCAM-1 also is an established biomarker to predict future or long-term acute coronary syndrome." (PMID 30505360, 2018). "This study suggests that VCAM-1, an inflammatory biomarker, may be a prognostic indicator of LV remodeling and dysfunction in patients with acute coronary syndromes." (PMID 40599142, 2025). "This study highlights the potential role of VCAM-1, a biomarker of inflammation and immune activation, as a prognostic indicator of impaired LV performance, as reflected by changes in left ventricular ejection fraction and left ventricular end-diastolic volume, following acute coronary syndromes." (PMID 40599142, 2025). "Therefore, the aim of this study was to investigate a possible relationship between circulating VCAM-1, ICAM-1, E-selectin or MMP9 and the extent of coronary lesions in patients without acute coronary syndrome nor post-infarction patients." (PMID 29846413, 2018).
arteriosclerosis (9 papers, 2007 to 2025). A vascular disorder characterized by thickening and hardening of the walls of the arteries. "Meanwhile, the abnormal activation of the IL6/JAK/STAT3 pathway can upregulate VCAM-1, accelerate endothelial cell damage, and promote arteriosclerosis." (PMID 40809841, 2025). "Vascular cell adhesion molecule 1 (VCAM-1) is essential for leukocyte recruitment and the development of arteriosclerosis." (PMID 38578497, 2024). "Numerous domestic and international studies have demonstrated that in arteriosclerosis, increased expression of VCAM-1 and ICAM-1 leads to intercellular adhesion, exacerbating vascular stenosis and thrombus formation." (PMID 39534464, 2024). "The vascular endothelium is thus a crucial site in the pathogenesis of arteriosclerosis, where the interaction between monocytes and endothelial cells is mediated by CAMs like VCAM-1 and ICAM-1." (PMID 39534464, 2024). "The myokines irisin and BAIBA mediated these effects by inhibiting vascular cell adhesion molecule 1 expression in vascular endothelial cells, which suppressed the progression of arteriosclerosis." (PMID 37554940, 2023). "The expression of intercellular adhesion molecule-1 (ICAM-1), vascular cell adhesion protein 1 (VCAM-1), and E-selectin increases in VECs during the initiation and progression of arteriosclerosis." (PMID 35053238, 2022). "For the first time, we investigated the levels of EphA2, PGRN, VCAM1, and Hcy in arteriosclerosis patients and evaluated the function of PGRN and EphA2 in Hcy-induced injury of ECs." (PMID 33510642, 2020). "We aimed to investigate the levels of progranulin (PGRN), Eph-receptor tyrosine kinase-type A2 (EphA2), vascular cell adhesion molecule-1 (VCAM-1), and Hcy in patients with arteriosclerosis and investigate their functions in Hcy-injured human umbilical vein endothelial cells (HUVECs)." (PMID 33510642, 2020). "In parallel to arteriosclerosis, enhanced cholangiocellular VCAM-1 expression was recently demonstrated in multidrug resistance gene (Mdr2/Abcb4) knockout mice (Mdr2-/-), a well characterized mouse model that closely mirrors the macroscopic and microscopic pathology of PSC." (PMID 17254334, 2007).
cardiac hypertrophy (9 papers, 2015 to 2025). "To investigate potential migration pathways involved in cardiac hypertrophy, we analysed murine hearts for the expression of myocardial homing factors (VCAM-1, SCF, SDF-1) interacting with the measured subpopulations of BMCs using quantitative RT-PCR." (PMID 25754690, 2015). "Together, these data show that VCAM-1 overexpression accelerates pathological cardiac hypertrophy." (PMID 36467095, 2022). "Next, we analyzed the inhibited effect of VCAM-1 inhibition on cardiac hypertrophy." (PMID 36467095, 2022). "VCAM-1 and SCF concentrations were increased in mice with cardiac hypertrophy compared to healthy control mice." (PMID 25754690, 2015). "The expression levels of VCAM-1 (interacting with VLA-4) and SCF (interacting with c-kit) were significantly up-regulated in mice with induced cardiac hypertrophy compared to healthy controls." (PMID 25754690, 2015). "In the present study, the protein expression of PARP16 was also increased in the heart tissue of Ang II-infused mice, accompanied with the upregulation of myocardial hypertrophy marker BNP, myocardial fibrotic markers (Collagen 1 and MMP2/9) and the inflammatory marker VCAM-1." (PMID 37219631, 2023). "G-CSF treatment in mice with cardiac hypertrophy showed a further increase of VCAM-1 and SCF, but without significance." (PMID 25754690, 2015).
metastatic disease (9 papers, 1997 to 2023). "Our data argue against the previous proposals to target VCAM1 as a therapeutic strategy to treat metastatic disease." (PMID 36828890, 2023). "99mTc-cAbVCAM-1 is therefore a validate tool to study the prognostic value of VCAM-1 in the metastatic disease." (PMID 31340603, 2019). "Levels of circulating ICAM-1 and VCAM-1 were increased both in patients with local and those with metastatic disease." (PMID 9667659, 1998). "Increased serum concentrations of VCAM-1 were associated with locally advanced and metastatic disease whereas ICAM-1 was significantly elevated both in local and in advanced/metastatic disease." (PMID 9400933, 1997). "Upregulation of VCAM-1 during metastatic disease has been previously reported for LECs and may contribute to immune cell recruitment by interactions with its binding partner integrin α4β128." (PMID 38012149, 2023). "The use of monocyte- and macrophage-derived vesicles as nanovehicles emphasizes on their ability to evade clearance by the mononuclear phagocyte system and the expression of α4β1 that interacts with the vascular cell adhesion molecule-1 (VCAM-1) of metastatic tumors." (PMID 35874757, 2022). "Tumors at all stages showed negative staining for E-cadherin, whereas metastatic tumor at all generations showed negative staining for E-cadherin, ICAM-1, VCAM-1, and CK8/18." (PMID 26847082, 2016). "These metastatic tumors revealed no detectable expression of CK8/18, E-cadherin, VCAM-1, and ICAM-1." (PMID 26847082, 2016). "Interestingly, E-cadherin, ICAM-1, VCAM-1 and CK8/18 are not expressed in the implanted and metastatic tumor tissues of nude mice, suggesting that the molecular and biological characteristics of the implanted and metastatic tumors are different from the original tissue obtained surgically." (PMID 26847082, 2016).
pulmonary hypertension (9 papers, 2017 to 2025). Increased pressure within the pulmonary circulation due to lung or heart disorder. "Therefore, the expression pattern and role of VCAM1 in pulmonary hypertension need to be further studied." (PMID 33816621, 2021).
brain inflammation (8 papers, 2012 to 2026). "The ability of the overexpression of vascular cell adhesion molecule-1 (VCAM-1) in inflammatory BECs to generate VCAM-1-coupled lipid NPs loaded with thrombomodulin mRNA to eliminate brain edema in a TNF-α-induced acute brain inflammation model in mice was studied." (PMID 40142945, 2025). "Therefore, the role of VCAM-1 may be more important than that of ICAM-1 in inflammatory brain diseases such as MS." (PMID 28671640, 2017). "A previous study suggested that VCAM-1 and ICAM-1 contribute differently to leukocyte action during brain inflammation, because the expression of adhesion molecules differs depending on tissue type." (PMID 28671640, 2017). "The brain endothelial cells (bEnd.3) express Vascular cell adhesion molecule 1 (VCAM-1), the receptor responsible for inflammatory cell adhesion, which binds very late antigen 4 (VLA-4) on migrating effector lymphocytes at the early stage of brain inflammation." (PMID 28481289, 2017).
Cirrhosis (8 papers, 2013 to 2025). A chronic disorder of the liver in which liver tissue becomes scarred and is partially replaced by regenerative nodules and fibrotic tissue resulting in loss of liver function. "VCAM-1 has been suggested to play a role in the pathogenesis of chronic hepatitis and cirrhosis, as its expression levels were found to be upregulated in chronic liver disease." (PMID 36034715, 2022). "VCAM-1 concentrations are elevated in the presence of liver diseases such as chronic hepatitis and cirrhosis." (PMID 31291245, 2019). "Meanwhile, it was also expressed in the hepatic parenchyma including the portal tract and the portal vein in BA patients, especially with advanced cirrhosis which suggested that ongoing cirrhosis could be mediated by VCAM-1 through humoral and cell-mediated immune interaction." (PMID 35626874, 2022). "In this regard, increased plasma concentrations of several angiogenic mediators, including angiopoietin 2, TEK tyrosine kinase endothelial (Tie2), intercellular adhesion molecule 3 (ICAM3), and vascular cell adhesion molecule 1 (VCAM1), are increased in patients with HPS and cirrhosis." (PMID 40171298, 2025). "A mouse model of hepatic cirrhosis was established and research was conducted into the effect of thalidomide on the expression of NF-κB, IKB, inter-cellular adhesion molecule-I (ICAM-I) and vascular CAM-1 (VCAM-1)." (PMID 23737889, 2013).
clear cell renal carcinoma (8 papers, 2016 to 2024). A malignant epithelial neoplasm of the kidney characterized by the presence of lipid-containing clear cells within a vascular network. "VCAM-1, a member of the immunoglobulin superfamily, is closely related to the development of malignant tumors, such as breast, ovarian, and clear cell renal carcinoma." (PMID 39160581, 2024). "In contrast, MSC-2 clusters derived from the bone marrow of patients with clear cell renal cell carcinoma metastases maintained the classic MSC markers NT5E and THY1 (CD90), but the expression of VCAM1, LEPR, and CXCL12 was reduced." (PMID 39156727, 2024).